CCL2 (C-C motif chemokine ligand 2)
Diseases named in the same sentence as CCL2 in open-access papers (continued):
Sharing a sentence is not in itself a finding about the gene and the disease.
tumor (continued). "These SVF cells do not have an “activated” phenotype as has been observed in adipose stromal cells from obese women, allowing for investigation of the effects of CCL2 expression within the developing tumor microenvironment." (PMID 32731354, 2020). "Various chemokines and cytokines promote macrophage recruitment to tumor tissues, such as C-C motif chemokine ligand 2 (CCL2), macrophage colony-stimulating factor (GM-CSF), VEGF, CXCL-12 and hypoxia-inducible factors (HIFs)." (PMID 32850861, 2020). "Tumor cell-derived Lnc-BM facilitated STAT3-dependent expression of CCL2 and ICAM1, which mediated macrophage recruitment and vascular co-option in the brain, respectively." (PMID 32083005, 2020). "Transferred T cells showed a significant migration towards xenograft tumor in response to tumor-derived CCL2, whose transmigrate was directly mediated by CCR2 recognition." (PMID 32483450, 2020). "In contrast, in some tumors, such as in non-small cell lung cancer, CCL2 participates in tumor immune evasion." (PMID 33182504, 2020). "In contrast with previous studies, which targeted the CCR2/CCL2 pathway primarily in alternative experimental models, we found enhanced tumor volumes in Ccr2-/- mice." (PMID 32668709, 2020). "The activation of NFκB and STAT3, as a result of hypoxia in the tumor niche, can also induce expression and release of CCL2 from CAFs." (PMID 33363032, 2020). "Over-expression of CCL2 increases tumor growth and bone metastasis through the recruitment of macrophages and osteoclast to tumor sites." (PMID 32971847, 2020). "After confirming their CCL2 production, we examined the in vivo effect of miR-155 deficiency in rejection of AT3 tumors by assessing tumor burden and tumor-infiltrating leukocyte composition." (PMID 32040476, 2020). "Endothelial cell survival and tumor angiogenesis are promoted by CC chemokines: CCL2, -11, -16, and -18, as well as by proangiogenic CXC-ELR (+) chemokine CXCL8." (PMID 32456359, 2020). "For example, they presented that conventional irradiation led to an increased release of CCL2, which in turn attracted monocytes at tumour sites and promoted their differentiation into TAMs." (PMID 32635552, 2020). "We found that reactive CAFs induce resistance to FSS to tumor cells by forming a protective cellular nodule and by soluble factors such as: CCL2, CCL7 and CXCL5." (PMID 32256977, 2020). "To address the mechanisms underlying the antitumor effects of celecoxib, we focused on the tumor microenvironment and examined the levels of chemokines CCL2 and CXCL10 and their receptors, CCR2 and CXCR3, respectively." (PMID 32943658, 2020). "Specifically, the recruited monocytes exposed to IFN-γ produce tumor necrosis factor-related apoptosis-inducing ligand (TRAIL), which induces cell death in TRAIL-sensitive tumor cells and stimulates secretion of CCL2 and IL-8 from tumor cells." (PMID 32824016, 2020). "In contrast, the CCR2 ligand CCL2, mainly expressed by VE-cadherin+ stromal/endothelial cells, has been found to profoundly increase as tumor grows." (PMID 32582203, 2020). "Many types of cells present in the primary and metastatic tumor microenvironments, including stromal cells, leukocytes, endothelial cells, and tumor cells, produce CCL2." (PMID 32471499, 2020). "Analysis of tumor tissue lysates as well as sera from LLC tumor-bearing mice treated with GB1275 showed a significant reduction in circulating CCL2 levels, compared to vehicle-treated controls." (PMID 32528880, 2020). "CCL2 and CSF-1 are important for inflammatory monocyte recruitment into the tumor site and differentiation into TAMs." (PMID 33293516, 2020). "ELF1 has been implicated in transcription regulation of several tumor-promoting genes including Tie2, MEIS1, CCL2, LUCAT1." (PMID 32795319, 2020). "COX-2 inhibition by acetylsalisylic acid (aspirin, ASA) prevented the CCL2-mediated accumulation of CD11b+Ly6GhiLy6Clo granulocytic MDSCs to the tumor microenviroment in mice with glioma." (PMID 32265903, 2020).
tumor (continued). "SHP has also been shown to suppress tumor cell proliferation and invasion via transcriptional repression of cyclin D1 and Ccl2 expression." (PMID 32807788, 2020). "Another study showed that CCL2 induced the migration of myeloid suppressor cells (MSCs) to tumor site, inducing tumor immune evasion." (PMID 31991677, 2020). "Taken together, these data suggest that myeloid progenitor cells are recruited from the bone marrow to the transplants of SVF/CCL2 humanized glands early in tumor formation." (PMID 32731354, 2020). "TAMs are recruited to the tumor site through tumor secretion of cytokines and chemokines, including ATP, CSF-1, CCL2, GDNF, GM-CSF HGF/SF, MCF-3, SDF-1, TNF and VEGF6,15." (PMID 32555306, 2020). "S100A4 also induces the secretion of further paracrine factors, such as IL-8 and CCL2, which in return, promote angiogenesis and recruitment of monocytes, creating an inflammatory milieu in the tumour microenvironment." (PMID 32722137, 2020). "Specifically, first, tumor cells secrete a large number of chemokines to recruit macrophages into tumor tissues, such as CCL2, CCL3, CCL5, and so on." (PMID 33224886, 2020). "Of note, TAMs directly participate in CCL-2 and IL-10 production, suggesting the existence of an autocrine amplification loop involved in their tumor-related recruitment and polarization." (PMID 33212945, 2020). "IL-4 is generated by both tumor cells and stromal cells, and IL-4 neutralization resulted in reduced levels of the chemokines CCL2, CCL11, and CXCL5 in the TME." (PMID 33178603, 2020). "In a CAC model, oral pre-treatment with S. gallolyticus exacerbates both inflammation (e.g., IL-6, IL-1β, IL-8, CCL2, TNFα) and tumor formation." (PMID 32962159, 2020). "Another study showed that tumor-entrained neutrophils also accumulated in the lungs via CCL2 and inhibited metastatic seeding in lungs by producing H2O2." (PMID 33322216, 2020). "Inhibition of CCL2 signaling or depletion of tumor cell-derived CCL2 diminished lung metastases in vivo." (PMID 33322216, 2020). "Tumor-associated monocytes/macrophages are recruited into the tumor microenvironment by chemokines such as SDF-1 and CCL2." (PMID 32555170, 2020). "Current evidence shows that CCL2 is involved in tumor initiation and progression, by mediating monocyte recruitment/maturation into TAMs, as well as acting on stromal and tumor cells to modulate angiogenesis, metastasis and cancer cell proliferation." (PMID 32784743, 2020). "Some of these chemokines are involved in the recruitment of cells into the tumor niche: CCL2/MCP-1 in the recruitment of TAMs, and CXCL1/GRO-α in the recruitment of neutrophils and myeloid-derived suppressor cells (MDSC)." (PMID 33114763, 2020). "Together these data demonstrate that humanization of mouse mammary glands with CCL2 expressing stromal cells enhances macrophage recruitment early in tumor formation." (PMID 32731354, 2020). "To investigate how early changes in tumor development lead to increased collagen deposition in end-stage SVF/CCL2 tumors, we examined early time points following transplantation of oncogenic breast epithelial cells." (PMID 32731354, 2020). "CSCs recruit macrophages to the tumor niche by producing pro-inflammatory cytokines and chemokines, such as CCL2, IL-6, IL-4, VEGF and TGF-ß." (PMID 33059744, 2020). "Significantly, CX3CL1 is not the only chemokine involved in this process, e.g., also important in the recruitment of microglia to GBM tumor are MCP-1/CCL2 and RANTES/CCL5." (PMID 32466280, 2020). "Other strategies involve the inhibition of their recruitment in the tumor microenvironment, such as interventions targeting the CCL2 axis by CCR5 receptor antagonists." (PMID 32580431, 2020). "We also compared expression of 24 CC chemokines in tumor tissues, which revealed that CCL2 was highest expressed in BC tissues." (PMID 33146700, 2020). "Different from TRAMP-C1, it was reported that the tumor microenvironment of LLC promoted Ccl2 expression." (PMID 32244522, 2020).
tumor (continued). "Tumor cells recruited CCR2+ MDSCs through their expression of high levels of MCP-1/CCL2, the ligand for chemokine CCR2." (PMID 33322474, 2020). "Macrophages are attracted to tumor sites expressing chemotactic factors such as CCL2, CCL5, CCL7, CCL8, CXCL1, and CXCL12." (PMID 31991604, 2020). "(A) Representative darkfield microscopy image of in situ hybridization for Ccl2 in sham and tumor (10 d.p.i) mouse brains." (PMID 32391790, 2020). "CCL2 expression within developing tumors also enhanced recruitment of myeloid progenitor cells from the bone marrow into the tumor site." (PMID 32731354, 2020). "CCL2 function extends beyond that and shows a significant role in the tumor microenvironment in affecting macrophage and modifying them towards tumor-promoting phenotype." (PMID 32455851, 2020). "Mechanistically, pro-tumor functions of Wnt5a in TAMs depended on CaMKII-ERK pathway-mediated CCL2 secretion." (PMID 32140070, 2020). "The tumor-promoting functions of Wnt5a in TAMs depended on CaMKII-ERK pathway-mediated CCL2 secretion." (PMID 32140070, 2020). "Hypoxia recruits TAM precursors from bone marrow to tumor lesion, through multiple mechanisms such as releasing chemoattractants like CCL2, CCL5, CXCL12, VEGFA, and endothelin and liberating some cellular contents like DAMPs from the hypoxic dying cell." (PMID 33505964, 2020). "An interesting candidate for marking both tumor cells and immune cells at the protein level is the chemokine CCL2 (chemokine, CC motif, ligand 2; synonym monocyte chemotactic protein 1 (MCP-1))." (PMID 32429318, 2020). "Together, mTOR signaling promotes the PEG-mediated CCL2 expression in both tumor cells and macrophages, thereby regulating macrophages chemotaxis to the tumor and acts as a potential target for anti-tumor immunotherapy." (PMID 32483450, 2020). "By the 6th day, the 4T1 cell-overexpressing CCL2 seemed to form more abnormal grape-like tumor structures." (PMID 33244467, 2020). "The majority of macrophages present in the tumor microenvironment are recruited from bone marrow-derived monocytes through the CC chemokine 2 (CCL2/CCR2) and colony stimulating factor 1 (CSF-1/CSF-1R) signaling pathways." (PMID 32326073, 2020). "Consistent with the role of CCL2 in cancer progression, serum CCL2 levels and CCL2 expression levels in tumor tissue have been reported as potential biomarkers in a variety of cancer patients." (PMID 33297571, 2020). "RT also triggers an influx of myeloid cells through the upregulation of the secretion of chemokines such as CCL2 by tumours, which can contribute to the generation of an immunosuppressive environment." (PMID 32112478, 2020). "We observed both increased CCL2 mRNA and protein expression from tumor lymph nodes of Ibtk+/- Eμ-myc compared to Ibtk+/+ Eμ-myc mice." (PMID 32019112, 2020). "Unexpectedly, after comparing mouse Ccl2 levels between tumor tissues and their derived primary cells, we found reduced, not increased, expressions in tumor tissues." (PMID 32244522, 2020). "Concerning CCL2, this chemokine is produced by cancer cells and is correlated with monocytes infiltration into the tumor site, this resulting in enhanced metastatic potential." (PMID 32854690, 2020). "The chemokine MCP-1 (CCL2) is important for the recruitment of bone marrow generated myeloid cells into the blood, and for the trafficking of MDSCs to tumor sites, by binding to the G protein-coupled receptor, CCR2." (PMID 33322474, 2020). "Specific signaling molecules, such as CCL2, CSF-1, cytokines, and complement components (i.e., C5), are able to rapidly recruit circulating inflammatory monocytes at sites of tumor growth." (PMID 33050070, 2020). "CCL2 directly manipulates T cell tropism toward tumor foci in a protective role, which is abolished by anti-CCL2 neutralizing treatment." (PMID 32483450, 2020). "LncRNAs are also involved in regulation of TAMs infiltration in tumor through affecting CCL2 expression." (PMID 32549757, 2020).
tumor (continued). "That is the case of Nr4a1, Ccl2, and Ccl3, which antagonize tumor growth by attracting tumor-suppressive immune cells." (PMID 33330473, 2020). "In KPC tumors, the epigenetic regulator HDAC5 inhibits Socs3, a negative regulator of CCL2, promoting CCL2 secretion and the recruitment of tumor-promoting macrophages to the TME." (PMID 33304355, 2020). "Tumor-derived CCL2 shapes macrophage polarization by GM-CSF and M-CSF, and positively correlates with TAM infiltration, tumor vascularization, and angiogenesis." (PMID 32653013, 2020). "CCR2-expressing cells migrate to the source of CCL2 and are frequently recruited to tumor tissue, where they differentiate into tumor-promoting TAMs." (PMID 31811337, 2020). "The production of cytokines, including CCL2 and IL-6, which are important in promoting tumor growth, is significantly inhibited by trabectedin in four different mouse tumor models." (PMID 32260363, 2020). "To determine the impact of reduced CCL2 activity on tumor growth when combined with anti-PD-1, we depleted CCL2 expression in NA13 cells using either of two different shRNAs." (PMID 33247183, 2020). "Mostly, the detection of CCL2 in tumors is considered a marker for tumor progression/metastasis, e.g., in cancers of the breast, prostate, colon, and thyroid glands." (PMID 32429318, 2020). "Both human PDAC and KPC tumor cells express high levels of CCL2, although normal cells also express this chemokine." (PMID 33304355, 2020). "Mechanistically, the pro-tumor effects of Wnt5a in TAMs were dependent on CaMKII-ERK pathway-mediated CCL2 production." (PMID 32140070, 2020). "They found that in tumor-bearing mice, sorafenib increased the number of TANs as well as CCL2 and CCL17 levels in the tumor." (PMID 32532960, 2020). "(B) Representative 40X confocal microscopy images of the VI from Ccl2mCherry sham and tumor mouse brains, 10 d.p.i., demonstrating that CCL2 protein expression is confined to meningeal macrophages, identified by CD206 labeling." (PMID 32391790, 2020). "In GBM, TAMs are recruited to the tumour site through various mediators, including CCL2, CX3CL1, CSF-1, GM-CSF and osteopontin released by neoplastic cells." (PMID 31973030, 2020). "Carlumab is a human antibody that binds to CCL2, which reduced tumor growth, infiltration of phagocytic macrophages and blood vessel density." (PMID 32326073, 2020). "For example, the prognosis for patients is worse when the expression of CCL2 in the tumor is elevated." (PMID 33182504, 2020). "In this scenario, the CCL2/CCR2 axis is attracting particular interest and plays multiple important roles in systemic tumor-associated myeloid cell responses." (PMID 32582203, 2020). "The secreted chemokines from tumor cells and stromal cells, such as macrophage colony-stimulating factor (M-CSF) and C-C motif ligand 2 (CCL-2), can induce and recruit monocytes to the tumor microenvironment." (PMID 33363016, 2020). "We first analyzed the expression of TNF-α, the TNFR1 ligand and CCL-2, a chemokine involved in monocytes/macrophage recruitment to tumor sites." (PMID 33202705, 2020). "The chemokine (C-C motif) ligand 2 (CCL2)/chemokine (C-C motif) receptor 2 (CCR2) signaling axis contributes to tumor progression through CCR2-mediated MDSC recruitment and/or accumulation." (PMID 31297636, 2020). "Since the early steps of tumorigenesis, cancer and stromal cells increase the number of TAMs in the tumor, by producing chemokines and growth factors (e.g., CCL2 and CSF1)." (PMID 33050070, 2020). "In many cancers, tumor-associated macrophages (TAMs) are constantly recruited to the tumor environment by the CCL2 chemokine, which attracts CCR2+ monocytes circulating in the blood." (PMID 33153193, 2020). "In vivo anti-CCL2 antibody treatment reduced the number of MAMs at metastatic sites and reduced overall tumor burden in breast cancer models." (PMID 33381449, 2020). "Blockade of either CCL2 or its receptor CCR2 has shown anti-tumor activity in various preclinical models." (PMID 32983125, 2020).
tumor (continued). "Consistent with higher secretion of CCL2 and Vegfα, upon orthotopic tumor engraftment, the TME of Rb-depleted cells showed higher angiogenesis and infiltration of CCR2-positive tumor-associated macrophages (TAMs) and MDSCs." (PMID 32244804, 2020). "CDDO-Me-mediated reductions in myeloid tumor cell numbers are likely attributable to significantly attenuated expression of CCL2, IL-10, and VEGF, which also regulate monocyte recruitment to TAMs37." (PMID 32300202, 2020). "Specific signals by chemokines, i.e., CCL2 and colony stimulating factors (CSF)-1, cytokines and components of complement recall monocytes to tumor sites." (PMID 32708142, 2020). "Several studies have reported tumor-promoting properties of CCL2 in accelerating metastasis, increasing angiogenesis, and recruiting immune suppressive macrophages to the tumor." (PMID 32528880, 2020). "It is likely that TILs are recruited to tumor tissues in part through pro-inflammatory chemokines (e.g., CCL2) and local angiogenesis." (PMID 32244522, 2020). "ZEB1 in TAMs, a TGF-β downstream transcription factor, induces the expression of CCR2, MMP9, and CCL2 in cancer cells to accelerate tumor growth." (PMID 33224886, 2020). "In comparing immune population differences between the bottom and top quartile of CCL2 tumor expression, a higher presence of activated DCs and natural killer cells, both producers of IFNγ, are observed in the CCL2 low tumors." (PMID 33247183, 2020). "In PDAC, RT leads to the production of CCL2, which recruits macrophages to tumor sites to support tumor proliferation and neo-angiogenesis after RT." (PMID 31611871, 2019). "These TAMs can be derived from resident macrophages or attracted from bone marrow and spleen to the tumor site thanks to the CCL2 (MCP-1) and CCL5 (RANTES) chemokines produced by the tumors, fibroblasts, endothelial cells, and even by the TAMs themselves." (PMID 31547627, 2019). "There is sufficient evidence that CCL2 recruits monocytes and macrophages in the tumor microenvironment." (PMID 31781676, 2019). "As shown in representative simulation images, the extracellular acidosis, created by excess tumour glycolysis, dynamically changes the macrophage phenotype represented by the Arg1 and Ccl2 expression." (PMID 31417189, 2019). "In this murine model, CCL2 production by GAMMs was induced by tumor-derived CCL20 and osteoprotegerin." (PMID 31225500, 2019). "PCR analysis showed that the cells of the TME produced more than 30-fold higher Ccl2 and corresponding Ccr2 genes when compared to tumour cells." (PMID 31160587, 2019). "For example, in mouse models of breast cancer metastasis, CCR2+ inflammatory monocytes are attracted to the metastatic microenvironment by CCL2-producing tumor cells, where they promote vascular permeability and extravasation in a VEGFA-dependent manner." (PMID 31497019, 2019). "The cells traffic through the circulation and are chemoattracted to the tumor microenvironment by a series of chemokines such as CCL2 and CXCL2 that are present in the tumor microenvironment." (PMID 31001479, 2019). "Macrophages are also a source of C-C motif chemokine ligand 2 (CCL2), and a variety of tumor-types express CCL2." (PMID 31823764, 2019). "dn-CCL2 fused to serum albumin to prolong its half-life in serum inhibits the homing in the lung of mice of MC38 tumor cell that synthesizes CCL2 and metastasizes in a CCL2-dependent manner." (PMID 31362364, 2019). "The mRNA induction in sorted CD14+ MΦ was manifold higher for CXCL10 and CCL2 as compared with tumor cells." (PMID 30850595, 2019). "Treatment with anti-LIF increased CXCL9 and decreased CCL2 expression, while inducing immune cell infiltration into the Matrigel surrounding the tumor specimen." (PMID 31186412, 2019). "We also dissected the mechanism behind the MAGEA3 role in tumor progression using western blot analysis and CCL2 neutralization." (PMID 31287009, 2019).